MGMT (O-6-methylguanine-DNA methyltransferase)
Diseases named in the same sentence as MGMT in open-access papers (continued):
Sharing a sentence is not in itself a finding about the gene and the disease.
glioblastoma (continued). "Here, we review the clinically relevant information that can be obtained by studying MGMT gene and whole-genome DNA methylation changes in glioblastomas, also highlighting benefits, including those of liquid biopsy, and pitfalls of the different detection methods." (PMID 35806153, 2022). "For example, the DNA methylation status of the MGMT promoter is currently utilized to determine whether therapeutic agents are effective in glioblastoma treatment." (PMID 35185591, 2022). "In glioblastoma, Oncobox method could effectively predict tumor response on temozolomide, a DNA-alkylating agent whose activity is antagonized by MGMT gene products." (PMID 35387112, 2022). "However, the Phase III CheckMate-498 study did not meet the primary endpoint of OS with nivolumab plus radiation in patients with newly diagnosed MGMT-unmethylated glioblastoma." (PMID 35204029, 2022). "We suggest that a threshold of 15% for methylation of MGMT promoter could have a prognostic role in newly diagnosed IDH wild-type glioblastoma patients, especially on overall survival." (PMID 35626029, 2022). "A radiomic model for prediction of MGMT promoter methylation status from tumor texture features in patients with recurrent glioblastoma was successfully established, providing a non-invasive approach to anticipate patient’s response to chemotherapy if biopsy cannot be performed." (PMID 33937035, 2021). "MGMT methylation in glioblastoma predicts response to temozolomide but dichotomizing methylation status may mask the true prognostic value of quantitative MGMT methylation." (PMID 34988453, 2021). "The genetic basis of MGMT gene methylation could help to explain individual differences in glioblastoma treatment response and most importantly, provide references for mapping the methylation Quantitative Trait Loci (meQTL) underlying the genetic regulation." (PMID 33588926, 2021). "In contrast to MGMT-status and extent of resection which both are well-described prognostic factors, multifocal disease has not previously been identified as an independent prognostic factor in glioblastoma patients treated with standard therapy." (PMID 33718145, 2021). "Once glioblastoma patients are dichotomized into highly and moderately vascularized tumor subgroups using rCBV, we observe a highly significant impact of MGMT status in patients with moderately vascularized tumors and only a non-significant trend in patients with highly vascularized tumors." (PMID 33001310, 2021). "MGMT promoter methylation has the most impact on clinical practice for patients with glioblastoma." (PMID 34638714, 2021). "However, further in vivo investigations and validations are necessary to confirm these findings and to improve and establish new treatment options for MGMT unmethylated glioblastoma multiforme with the combination of lomeguatrib and ionizing radiation." (PMID 34202589, 2021). "In this study, we intended to analyze whether a methylated MGMT promoter could outweigh the burden of incomplete resection in IDH-wildtype glioblastoma patients." (PMID 34185258, 2021). "Methylation of the O6-methylguanine-DNA-methyltransferase (MGMT) promoter may be used to decide whether elderly glioblastoma patients will benefit from treatment with Temozolomide alone instead of radiotherapy." (PMID 34504133, 2021). "Promoter methylation of MGMT occurs in approximately 40% of glioblastoma." (PMID 34210107, 2021). "However, given the percentage of about 65% of glioblastoma patients with an unmethylated MGMT promoter methylation status, this treatment strategy is limited to only a minority of glioblastoma patients." (PMID 33673490, 2021).
glioblastoma (continued). "Standard 6-week chemoradiation was feasible for “real-life” elderly patients diagnosed with glioblastoma with unknown MGMT status, even in cases of post-operative neurological disabilities." (PMID 34764361, 2021). "Through our previous studies we have demonstrated that Acridone derivatives have DNA intercalating property which implicates that these derivatives might also be effective in killing resistant glioblastoma through MGMT-independent mechanisms as well." (PMID 33791212, 2021). "Finally, we aimed to investigate the potential benefit of increasing the number of adjuvant temozolomide cycles in different groups of glioblastoma patients according to their MGMT methylation status and tumor vascularity." (PMID 34771583, 2021). "Compared to other studies, a different cut-off to categorize MGMT promoter methylated and unmethylated glioblastomas might also have an impact." (PMID 34185258, 2021). "The clinical significance of HOXA Transcript Antisense RNA, Myeloid-Specific 1 (HOTAIRM1) was determined by analyzing HOTAIRM1 in multiple glioblastoma gene expression data sets for associations with prognosis, as well as, IDH mutation and MGMT promoter methylation status." (PMID 34584066, 2021). "Hence, in glioblastoma patients with methylated MGMT promoter, combined (chemoradiation) treatment is more efficient, and a survival advantage can be observed compared to patients with unmethylated MGMT promoter." (PMID 34477324, 2021). "Thus, the flow cytometry data on cell cycle and cell death of the present study confirms the relative temozolomide resistance of MGMT promoter-unmethylated glioblastoma." (PMID 34827559, 2021). "In summary, we could clearly demonstrate that lomeguatrib significantly inactivated MGMT protein in the three tested MGMT promoter unmethylated human glioblastoma cell lines already at low concentrations and short treatment times (>6 h)." (PMID 34202589, 2021). "In this study, we aimed at evaluating whether the rCBV is a modulating factor of the prognostic effect of MGMT methylation status in patients with glioblastoma treated with TMZ." (PMID 33001310, 2021). "Additionally, MGMT promoter methylation status differed between the three donors, as glioblastomas of the donors of GSCs_a and GSCs_b depicted MGMT promoter methylation in contrast to the glioblastoma of donor GSCs_c." (PMID 33800955, 2021). "In particular, our result indicated that in the TCGA cohort, at a given instant in time, a glioblastoma patient exhibiting an HSC signal ≥0.54 was 88% as likely to die as someone showing an HSC signal <0.54, adjusting for age, MGMT promoter methylation and IDH mutations." (PMID 34162860, 2021). "Hence, MGMT promoter methylation in glioblastoma cannot be considered as a significant factor for long survival." (PMID 34257620, 2021). "Interestingly, though, more than 20% of patients in the iPDT series survived more than two years after malignant glioma recurrence irrespective of time to PDT and later salvage treatments and even with MGMT-unmethylated primary glioblastomas." (PMID 33917116, 2021). "The DNA repair protein MGMT is a key mediator of resistance to TMZ in newly diagnosed glioblastoma." (PMID 33575479, 2021). "Based on promising results from radiomic approaches to predict O6-methylguanine DNA methyltransferase promoter methylation status (MGMT status) and clinical outcome in patients with newly diagnosed glioblastoma, the current study aimed to evaluate radiomics in recurrent glioblastoma patients." (PMID 33937035, 2021). "The opposite was true for elderly glioblastoma with MGMT promoter-unmethylated glioblastoma." (PMID 32748120, 2021). "We thus selected a homogeneous population of IDH-wildtype glioblastoma in adults, collected the MGMT promoter methylation status when available, and included patients from 2012 to 2018 to ensure that they were treated during the current era with similar surgical, anesthetic and oncological care." (PMID 34200799, 2021).
glioblastoma (continued). "However, a difference was clearly seen among glioblastoma patients with unmethylated MGMT promoter who were treated with radiation vs. those who received chemoradiotherapy (p-value = 0.031)." (PMID 34257620, 2021). "On that account, because it was found robust, comparable to IDH mutation status, and superior to MGMT methylation status in most of the comparisons, we propose FREM2 pathway activation as a novel robust predictor of unfavorable prognosis of glioblastoma patients." (PMID 34439271, 2021). "This may argue for giving patients with PMMRDIA access to first line experimental treatments as increasingly done in patients with MGMT unmethylated glioblastoma, IDH-wt." (PMID 33216206, 2021). "We used NanoString GeoMx® Digital Spatial Profiling (DSP) technology in 10 cases of IDH-wild-type glioblastoma to quantify 27 immunooncology protein targets between ROIs in MGMT methylated and unmethylated tumours, additionally comparing tumour core and invasive margin regions." (PMID 33995529, 2021). "MGMT promoter methylation status has crucial prognostic importance in glioblastomas." (PMID 34858308, 2021). "Therefore, extending our work, the present study investigated the role and significance of the second promoter in MGMT transcription in human glioblastoma cells." (PMID 34201219, 2021). "Notably, the close homologue of Ada in eukaryotes, MGMT, has been shown to be expressed heterogeneously across cells in glioblastoma tumours." (PMID 34850170, 2021). "However, different nuclear transcription factors as SP1, AP-1, NF-kappa B, and HIF-1alpha, can activate the transcription of MGMT gene in glioblastoma." (PMID 33680961, 2021). "However, glioblastomas with unmethylated MGMT promoter, who received chemoradiotherapy mainly TMZ therapy, had a late tumor recurrence." (PMID 34257620, 2021). "It is important to note that for these experiments, glioblastoma cells that lack MGMT were used." (PMID 34944906, 2021). "Studies on MGMT expression in “pediatric glioblastomas” have demonstrated little alteration in the methylation promoter status in children, which may explain the reduced efficacy of TMZ in children compared to adults." (PMID 34858308, 2021). "At present, the US Food and Drug Administration has granted a fast track for paxalisib, a PI3K inhibitor, to treat newly diagnosed glioblastoma patients with unmethylated MGMT gene promoter, who have completed preliminary radiotherapy and temozolomide treatment." (PMID 34557405, 2021). "Furthermore, in a recently published randomized phase 3 clinical trial, additional application of alkylating agent lomustine to TMZ standard therapy was accompanied by a survival benefit for patients with newly-diagnosed MGMT promoter methylated glioblastoma." (PMID 33673490, 2021). "Alternatively, metronomic application of TMZ might suffice to sensitize relatively resistant glioblastoma cells to this drug, as MGMT is a suicide enzyme that is destroyed upon de-alkylating a base." (PMID 34485282, 2021). "• MGMT methylation improves prognosis in glioblastoma patients with moderate vascular profile." (PMID 33001310, 2021). "Additionally, there are conflicting reports on lobar distribution, in which glioblastoma with MGMT methylation were more frequently located in the parietal and occipital lobes, while those without were located more frequently in the temporal lobes." (PMID 32477929, 2020). "Similarly, for MGMT‐methylated glioblastoma, the standard regimen of concurrent and adjuvant TMZ is likely transient until more optimal therapy can be defined." (PMID 31701682, 2020). "Extensive resection was more beneficial for patients with MGMT methylated glioblastoma." (PMID 32766140, 2020). "Finally, we identified 2 SNVs in the promoter region of MGMT, and one of them (rs1625649) had prognostic impact on patients with MGMT methylated glioblastoma." (PMID 32563269, 2020).
glioblastoma (continued). "Taken these factors together miR-181d as a tumor suppressive miRNA could be of great use in treating glioblastoma patients to increase sensitivity to TMZ by directly targeting MGMT mRNA." (PMID 32354046, 2020). "PD‐1 blockade may enhance the antitumor activity of autologous CAR‐T cells engineered to recognize EGFRvIII+, MGMT‐unmethylated glioblastomas that are poorly responsive to standard‐of‐care alkylating chemotherapy." (PMID 32508018, 2020). "Importantly, MGMT, which is involved in the treatment‐induced resistance of glioblastomas, was also decreased by imipramine." (PMID 32149465, 2020). "Age, performance status, extent of resection, the presence of rapid early recurrence before radiotherapy, MGMT gene promoter methylation, ability to finish concomitant chemoradiotherapy, and adjuvant chemotherapy significantly influence the prognosis of glioblastoma patients." (PMID 32719739, 2020). "However, preliminary results with veliparib in the VERTU trial, a randomized Phase II trial in MGMT-unmethylated glioblastoma patients found that the combination of veliparib with chemoradiation was well tolerated, but did not improve outcomes." (PMID 33614476, 2020). "We provide substantial evidence that the PLEKHG5/RAB26 pathway is involved in the regulation of autophagy, cell proliferation, cellular morphology, apoptosis and even MGMT expression as well as promoter regulation at least in the U251-MG glioblastoma model system under investigation." (PMID 33318498, 2020). "Visual examination suggested that when compared with MGMT unmethylated glioblastoma, MGMT methylated glioblastoma were more frequently located near bifrontal and left occipital periventricular area and less frequently near the right occipital periventricular area." (PMID 32477929, 2020). "There are conflicting reports about a differential topographical distribution of glioblastoma with vs. without MGMT promoter methylation, possibly caused by molecular heterogeneity in glioblastoma populations." (PMID 32477929, 2020). "MGMT promoter methylation status is observed in the 50% of glioblastoma patients." (PMID 33317554, 2020). "MGMT methylation status is determined for all glioblastomas in 37% of laboratories." (PMID 32025325, 2020). "There have been many studies on the effects of MGMT on TMZ resistance in glioblastoma treatment." (PMID 32086739, 2020). "Therefore, at least in glioblastoma multiforme, MGMT methylation status is a predictive biomarker for increased response to temozolomide therapy." (PMID 32841306, 2020). "Depletion of PRPF19 expression resulted in the anticipated sensitization to temozolomide in glioblastoma cell lines and primary cell cultures, and may therefore, be investigated further as a predictive marker in MGMT promoter unmethylated glioblastoma." (PMID 32991787, 2020). "The effect of upfront alkylating agents vs targeted treatments in MGMT promoter unmethylated glioblastoma on its prognostic impact could be answered by subgroup analysis of our currently recruiting N2M2 clinical study." (PMID 32991787, 2020). "In MGMT methylated glioblastoma, when compared to >5 cm3 residual CE tumor (224 days; 95% CI 164–284), we observed a significantly longer median overall survival for a residual CE tumor volume of 1–5 cm3 (470 days; 95% CI 330–610; p < 0.0001) and 0–1 cm3 (536 days; 95% CI 319–752; p = 0.003)." (PMID 32766140, 2020). "Secondly, this study focuses on the IDH wild-type with MGMT promoter unmethylated glioblastoma." (PMID 32851059, 2020). "The most successful clinical application is the methylation status of the O6-methylguanine-DNA-methyltransferase (MGMT) promoter, which predicts radiation response and prognosis in glioblastoma Epigenetic control also plays an important role in radiation response in NSCLC." (PMID 32693792, 2020).
glioblastoma (continued). "This figure in fact shows that not any statistically significantly discriminating brain area between MGMT methylated and unmethylated glioblastoma could be found (p < 0.05)." (PMID 32477929, 2020). "The addition of TMZ to short-course radiotherapy was associated with a significant survival benefit over short-course radiotherapy alone among elderly patients with newly diagnosed glioblastoma, which was particularly evident in patients with a methylated MGMT status." (PMID 32257553, 2020). "The nature of the relationship between BCL6 and MGMT expression in glioblastoma is unclear, but could provide a double hit of therapy resistance—MGMT would repair the TMZ-mediated damage, while BCL6 induced by radiotherapy and TMZ would enhance survival." (PMID 32320427, 2020). "More recently, in an effort to improve upon the standard of care regimen using TMZ, a phase 3 trial was performed comparing the combination of lomustine and TMZ vs. standard TMZ in patients with newly diagnosed glioblastoma with methylated MGMT promoter, with a median survival of 31.4 m vs. 48.1m." (PMID 33614476, 2020). "Recurrent glioblastoma with unmethylated MGMT has a poor prognosis." (PMID 33634023, 2020). "Subsequently, the difference in median of the 23Na concentration of this whole tumor area was compared between IDH-mutated and IDH wild-type gliomas as well as MGMT methylated and MGMT not-methylated glioblastomas using Whitney-Mann U-tests." (PMID 33002860, 2020). "We found high correlations among measurements of tumoral size by the three methods, with pre-operative FLAIR-T2 hyper-intensity areas and volumes providing the optimal neuroimaging biomarker to predict OS in primary glioblastoma patients, together with age ≥ 65 years and MGMT methylation." (PMID 32984040, 2020). "In addition, DSF, in combination with 1-(2-chloroethyl)-1-nitrosourea (BCNU), strongly inhibited MGMT (O6-methylguanine-DNA methyltransferase) in vitro and in in T98 glioblastoma xenografts." (PMID 33260923, 2020). "Standard chemotherapy in glioblastoma is based on alkylating agents such as temozolomide and studies have long shown that the effectiveness of temozolomide therapy depends on the methylation status of the MGMT gene." (PMID 32631437, 2020). "These markers have not been validated in an independent data set yet and an effect of differential DDR gene methylation in IDH wild‐type glioblastomas dependent on the clinically relevant MGMT promoter methylation is unknown." (PMID 32991787, 2020). "Regarding glioblastoma MGMT promoter methylation seems to be the gold standard in clinical routine." (PMID 32841306, 2020). "MGMT is methylated in ~50% of patients with newly diagnosed glioblastoma." (PMID 32477929, 2020). "This study is supported by another reporting that increased expression of miRNA-221/222 correlated with enhanced DNA damage and apoptosis in glioblastoma multiforme in response to temozolomide, due to repression of the miRNA-221/222 target, the DNA repair protein MGMT." (PMID 31979312, 2020). "However, even in the best-case scenarios when the MGMT gene is silent, glioblastoma still remains incurable." (PMID 33020527, 2020). "Several studies have shown that methylation of MGMT promoter can predict whether alkylating agents can be of benefit in glioblastoma and low-grade gliomas." (PMID 32010632, 2019). "In addition, results from a phase III clinical trial prospectively indicate that MGMT promoter methylation status can be used as a biomarker to predict good prognosis of glioblastoma patients treated with TMZ." (PMID 32010632, 2019). "Therefore, we used MSP and pyrosequencing (PYR) to analyze MGMT methylation both in tumor tissue and in paired blood samples from a homogeneous cohort of unresected glioblastoma patients and compared the results of the four analyses." (PMID 31366977, 2019).